TFF3 (trefoil factor 3)
Diseases named in the same sentence as TFF3 in open-access papers (continued):
Sharing a sentence is not in itself a finding about the gene and the disease.
liver cancer (2 papers, 2019 to 2021). An epithelial or non-epithelial malignant neoplasm that arises from the liver. "In support of these findings, literature evidence has also reported that TFF3 reduces doxorubicin sensitivity in gastric and liver cancer." (PMID 31658702, 2019).
lung squamous-cell carcinoma (2 papers, 2012 to 2019). "TFF3 has been identified as a novel biomarker to distinguish between lung adenocarcinoma (ADC) and lung squamous-cell carcinoma (SCC)." (PMID 31685806, 2019). "It was observed that >90% of lung ADCs were TFF3-positive, whereas no expression of TFF3 was observed in lung squamous-cell carcinomas (SCC), suggestive of TFF3 as a novel biomarker to distinguish between lung ADC and SCC19." (PMID 31685806, 2019).
metastasis (2 papers, 2014 to 2017). The spread or migration of cancer cells from one part of the body (where they first appeared) to another. "Expression of TFF3 protein was significantly associated with larger tumour size (P = 0.002), lymph node metastasis (P = 0.004), and higher disease stage (P = 0.040)." (PMID 25266665, 2014). "We have also previously reported a positive correlation of TFF3 expression with tumour size, lymph node metastasis, higher stage and poorer survival outcome in ER+ BC." (PMID 29100386, 2017).
mucinous adenocarcinoma (2 papers, 2013 to 2023). An invasive adenocarcinoma composed of malignant glandular cells which contain intracytoplasmic mucin. "However, the prevalence of TFF3 mRNA in primary samples appeared similar to that reported by IHC, with consistently higher expression in mucinous carcinomas (p<0.01)." (PMID 24023729, 2013). "TFF3 is essential for the transcriptional regulation of these molecules, and may cooperate with RPS4X to eventually lead to the mucinous adenocarcinoma mucus phenotype." (PMID 36690709, 2023).
mucositis (2 papers, 2015 to 2017). Mucositis is inflammation and damage of the mucous membranes lining the mouth and other parts of the gastrointestinal (GI) tract. "In contrast to our results, positive correlations between TFF3 and -2 expression and age have been observed in healthy children compared to children suffering from mucositis." (PMID 29028798, 2017). "In a methotrexate-induced mucositis model, TFF3 peptides were also minimized during acute phase, but reemerged during regeneration." (PMID 26390128, 2015).
multiple myeloma (2 papers, 2016 to 2024). "By contrast, incubation of cells with a purified λ light chain preparation from a patient with multiple myeloma provoked the presence of TFF3 in the cell supernatant." (PMID 27066010, 2016).
nephrolithiasis (2 papers, 2013 to 2018). The presence of a calculus in the pelvis of the kidney; this is most often composed of mineral salts and proteins. "TFF2 has been demonstrated to be the predominant TFF peptide excreted in urine, and significantly increased urine TFF2 levels, together with occasionally increased TFF3 levels have been observed in patients suffering from nephrolithiasis." (PMID 24282531, 2013). "In the human urinary tract, TFF3 is detected as the most abundant form followed by TFF1, while urine TFF2 and TFF3 are increased in patients with nephrolithiasis." (PMID 29850501, 2018).
non-alcoholic steatohepatitis (2 papers, 2022 to 2025). "EPA was also statistically significantly increased in the livers of Tff3−/− females compared to WT controls, while significantly reduced levels were found in patients diagnosed with MAFLD and more severe forms of the disease such as non-alcoholic steatohepatitis compared to healthy controls." (PMID 40426854, 2025).
obstructive sleep apnea (2 papers, 2017 to 2023). "Factors associated with trefoil factor family peptide 3 (TFF3) level and salivary flow rate in patients with obstructive sleep apnea (OSA) by linear regression analysis." (PMID 37183529, 2023). "Baseline characteristics, physical signs, laboratory results, trefoil factor family peptide 3 (TFF3), and flow rate of patients with and without obstructive sleep apnea." (PMID 37183529, 2023). "Trefoil factor family peptide 3 (TFF3) level and salivary flow rate in patients with and without obstructive sleep apnea (OSA)." (PMID 37183529, 2023).
oral diseases (2 papers, 2017 to 2024). "The established ELISA will be a valuable tool for facilitating the investigation of the physiological roles and the diagnostic values of TFF3 in oral diseases." (PMID 29151819, 2017). "TFF3 is an important biomarker to determine the activity and association of periodontal and systemic diseases.Established ELISA will be a valuable tool for facilitating the investigation of the physiological roles and the diagnostic values ofTFF3 in oral diseases." (PMID 39917209, 2024). "Previous studies have demonstrated the altered expression of TFF3 in saliva and in oral tissues from patients with various oral diseases." (PMID 29151819, 2017). "However, an explanation for the changes in the expression of TFF3 in various oral diseases remains unclear." (PMID 29151819, 2017).
oral mucositis (2 papers, 2017 to 2021). Inflammation of the mucous membranes of any of the structures in the mouth. "As TFF3 has also been successfully used in the treatment of oral mucositis in cancer patients, an attempt to treat cases of OSA with recombinant human TFF3 would appear promising." (PMID 29028798, 2017). "Thus, on the one hand, TFF peptides (especially homodimeric TFF3) can be expected to protect from chemotherapy- or radiotherapy-induced oral mucositis." (PMID 34830103, 2021).
pancreatic carcinoma (2 papers, 2021 to 2022). "Previous studies demonstrated significantly increased expression of TFF3 in human pancreatic carcinoma tissue." (PMID 35332126, 2022).
Stroke (2 papers, 2019 to 2022). Sudden impairment of blood flow to a part of the brain due to occlusion or rupture of an artery to the brain. "HS diet-fed Tff3 deficient mice seem to be less susceptible to stroke injury." (PMID 31635131, 2019). "Furthermore, TFF3 deficiency may also affect vascular function and stroke outcome." (PMID 35039476, 2022). "We aimed to study the effects of one week of HS diet (4% NaCl) on vascular function and stroke induced by transient occlusion of middle cerebral artery in Tff3−/− and wild type (WT/C57BL/6N) mice." (PMID 31635131, 2019). "In conclusion, present study confirmed that Tff3 depletion seems to partially impair vascular function and worsen the outcomes of stroke, which is moderately affected by HS diet." (PMID 31635131, 2019). "In conclusion, Tff3 depletion seems to partially impair vascular function and worsen the outcomes of stroke, which is moderately affected by HS diet." (PMID 31635131, 2019). "We compared the level of eIF2α activation in liver of WT and Tff3−/− mice on LS diet which showed difference in stroke intensity." (PMID 31635131, 2019). "Similarly, TFF3−/− mice has been shown to induce hearing impairment, accelerated presbycusis, and worsened stroke outcomes." (PMID 35039476, 2022). "TFF3−/− mice may be a useful model to study the pathogenic process of inflammatory enteritis, stroke, NAFLD and keratitis, and it is of great significance for disease treatment and drug development targeting TFF3." (PMID 35039476, 2022). "Transgenic Tff3−/− gene knockout mice (Tff3−/−/C57BL/6N) have changes in lipid metabolism which may affect vascular function and outcomes of stroke." (PMID 31635131, 2019). "It seems that short-term high salt diet has not augmented the stroke in Tff3−/− HS mice, because the infarction was similar between Tff3−/− LS and Tff3−/− HS mice, possibly due to short duration of the HS diet." (PMID 31635131, 2019). "It is possible that Tff3−/− mice, due to changes of lipid metabolism, have changes in the balance of vasoactive prostaglandins, which could affect their vascular reactivity to stimuli such as FID and may also affect the ability of neuronal tissue to sustain ischemia in stroke." (PMID 31635131, 2019).
tuberculosis (2 papers, 2017 to 2026). A chronic, recurrent infection caused by the bacterium Mycobacterium tuberculosis. "LPS, sCD14, LBP, EndoCAB and TFF3 showed significant trends in patients with positive biomarkers of tuberculosis dissemination." (PMID 42282041, 2026). "Patients with HIV-tuberculosis who died presented with higher concentrations of TFF3, cystatin C, and NGAL." (PMID 28363198, 2017). "Likewise, TFF3, a marker of intestinal damage, was elevated in patients with HIV-tuberculosis and associated with decreased survival time." (PMID 28363198, 2017). "Markers of intestinal damage (TFF3) and kidney injury (cystatin C and NGAL) were increased in patients with HIV-tuberculosis compared with HIV-infected controls." (PMID 28363198, 2017).
Acidosis (1 paper, 2022). Abnormal acid accumulation or depletion of base. "While angiopoietin 2 (Angpt-2) and P-selectin were associated with TFF3, I-FABP was correlated with soluble Fms-related receptor tyrosine kinase 1 (sFlt-1) as well as soluble vascular cell adhesion molecule 1 (sVCAM-1) in children with acidosis." (PMID 36069443, 2022).
acute tubular necrosis (1 paper, 2018). "In AKI of patients with acute decompensation of liver cirrhosis, urine TFF3 levels are significantly increased, particularly in acute tubular necrosis, compared to patients without AKI." (PMID 29850501, 2018).
adenoid cystic carcinoma (1 paper, 2019). A malignant tumor arising from the epithelial cells. "While little is known about TFF3 in the context of adenoid cystic carcinoma, there are reports indicating that it is involved in epithelial tissue healing and restitution, which may explain the role for its high expression following injurious stimuli to LGACC tumors." (PMID 30728899, 2019).
Allergy (1 paper, 2019). An allergy is an immune response or reaction to substances that are usually not harmful. "In this study, we have investigated (a) expression levels of TFF1 and TFF3, (b) tissue localization of the corresponding TFF peptides, and (c) the effects of bacterial colonization or infection and the presence of allergy on the target gene expression in sinonasal tissue from CRSwNP patients." (PMID 31683988, 2019).
amyloid (1 paper, 2014). "While several of the CSF biomarkers hint at immune-mediated links between responses to amyloid deposition and brain volume loss, the function of TFF3, which we found to be the single strongest predictor of neurodegeneration across the spectrum of brain amyloidosis, is unknown." (PMID 25072324, 2014).
anaplastic thyroid cancer (1 paper, 2016). "Along this line, forced expression of TFF3 significantly reduced proliferation of anaplastic thyroid cancer cells." (PMID 27626280, 2016).
asphyxia (1 paper, 2020). A state of general hypoxia and hypercapnia (abnormally elevated carbon dioxide (CO2) levels in the blood), resulting in acidosis, which affects all tissues in the body. "We found that among infants who developed NEC, these who were exposed to perinatal asphyxia have significantly higher levels of urinary TFF-3 and SAA than those who were not." (PMID 32190704, 2020).
atopic dermatitis (1 paper, 2024). "The elevated TFF‐3 concentration may be related to the intensive release from goblet cells to repair the damaged epithelial barrier associated with intestinal epithelial barrier damage in dogs with atopic dermatitis." (PMID 38648253, 2024). "Serum concentrations of IAP (p < 0.01), TFF‐3 (p < 0.01), IgE (p < 0.01), IL‐4 (p < 0.01) and IL‐13 (p < 0.01) were significantly higher in dogs with atopic dermatitis, compared to the healthy ones." (PMID 38648253, 2024). "Pearson correlation analysis between serum IAP, I‐FABP, TFF‐3, IgE, IL‐4, IL‐13, monocyte and eosinophil parameters in dogs with atopic dermatitis." (PMID 38648253, 2024). "In the present study, serum TFF‐3 concentrations were found to be statistically significantly higher in the dogs with atopic dermatitis, compared to the healthy dogs." (PMID 38648253, 2024). "Elevated serum concentrations of IAP and TFF‐3 may indicate the possibility of the development of a leaky gut in dogs with atopic dermatitis." (PMID 38648253, 2024). "In the present study, it was interpreted that the increase in the concentrations of TFF‐3 (p < 0.012) and IAP (p < 0.001), which repair intestinal mucosal barrier damage in dogs with atopic dermatitis, may indicate the presence of long‐term damage in the intestine." (PMID 38648253, 2024).
bacteremia (1 paper, 2024). "We measured intestinal fatty acid-binding protein, trefoil factor-3, and citrulline 48 h before bacteremia onset." (PMID 38536623, 2024).
benign prostatic hyperplasia (1 paper, 2017). A non-cancerous nodular enlargement of the prostate gland. "Although we have previously reported that the TFF3 promoter is hypomethylated in PC tissue samples, this was based only on a small patient sample set (10 PC vs. 12 benign prostatic hyperplasia (BPH) tissue samples)." (PMID 28930171, 2017).
benign thyroid tumours (1 paper, 2012). "Our results confirm their findings of a lower TFF3 mRNA expression in malignant vs benign thyroid tumours as well as in malignant follicular thyroid neoplasia vs FA." (PMID 22223087, 2012).
bone metastasis (1 paper, 2018). Transfer of a neoplasm from its primary site to bones. "The high level of TFF1 mRNA was related to the site of metastasis to show that 77.8% of cases had bone metastasis, while 75% of cases with high TFF3 mRNA level showed lymph node involvement and 68.8% showed lung metastasis." (PMID 29977293, 2018).
Brain Tumor (1 paper, 2022). "In the past, homodimeric TFF3 was reported to interact in vitro with the agglutinin Deleted in Malignant Brain Tumor 1/gp340 (DMBT1gp340), a glycoprotein involved in mucosal innate immunity (review:)." (PMID 36499686, 2022).
carcinoma in situ (1 paper, 2019). "There was a variable expression of TFF3 by malignant epithelial cells in intraductal carcinoma in situ ranging from absence of any expression, to low expression, to intermediate expression and high expression." (PMID 30744593, 2019).
chronic liver failure (1 paper, 2023). Liver failure that develops slowly and gradually for some time, possibly for years, often as the result of cirrhosis, or malnutrition. "Noteworthy, TFF-3 levels are influenced by the liver function, where acute-on-chronic liver failure significantly increase urinary TFF-3." (PMID 38139297, 2023).
chronic rhinosinusitis (1 paper, 2019). Chronic form of sinusitis. "Considering that bacterial infection and formation of biofilms is one of the predisposing factors in the cascade of events that leads to chronic rhinosinusitis, we can assume that TFFs, and particularly TFF3, have an important role in defending the epithelial surface from bacterial colonization." (PMID 31683988, 2019). "We have detected differential expression of TFF1 and TFF3 genes and peptides in sinonasal mucosa of patients with CRSwNP, where they could play an important role in mucosal defense from bacterial infection and the development of chronic rhinosinusitis." (PMID 31683988, 2019).
coccidiosis (1 paper, 2024). A parasitic infection caused by Coccidia. "In dogs with isosporiasis (I. B. Yildiz & Ok, 2022) and in calves with coccidiosis, there was no statistical difference in serum TFF‐3 concentration, compared to healthy animals before treatment, but there was a significant increase after treatment." (PMID 38648253, 2024).
congenital heart disease (1 paper, 2025). A heart disease that is present at birth. "This study evaluated the combination of IFABP and TFF3 in urine and blood as perioperative biomarkers in children with congenital heart disease (CHD)." (PMID 41246027, 2025). "Serum and urine samples from 85 children with congenital heart defects were analyzed pre- and postoperatively at 6 time points focusing on IFABP and TFF3." (PMID 41246027, 2025).
COVID-19 (1 paper, 2021). A disease caused by infection with severe acute respiratory syndrome coronavirus 2. "COVID-19 patients who had dialysis or genitourinary disorder had higher levels of osteopontin, GST, and TFF3 (FDR < 0.1 or <0.05)." (PMID 34960684, 2021).
Down syndrome (1 paper, 2025). "Similarly, elevated levels of TFF3 in amniotic fluid from Down syndrome pregnancies have been interpreted as markers of epithelial stress and inflammation rather than direct aneuploidy-driven regulation." (PMID 41614738, 2025).
duodenal cancers (1 paper, 2022). "Meanwhile, several upregulated genes in CRC malignant cells such as RPLP2, RPL36A, TFF3 have the increasing expression tendency in malignant cells from GC, duodenal cancers, jejunal cancers to CRC." (PMID 36104333, 2022).
dyspepsia (1 paper, 2015). An uncomfortable, often painful feeling in the stomach, resulting from impaired digestion. "The Cytosponge-TFF3 test is safe and generally acceptable to patients with symptomatic reflux or dyspepsia undergoing investigation, and for those patients with BE undergoing surveillance." (PMID 25634542, 2015).
endometrial adenocarcinoma (1 paper, 2014). "It was noted that expression of TFF3 in endometrial adenocarcinoma was positively correlated with ER expression in the studied cohort." (PMID 25266665, 2014).
fibrocystic disease of (1 paper, 2019). "There was also increased expression of TFF3 by epithelial cells forming the lining of cysts in fibrocystic disease of the breast." (PMID 30744593, 2019).
Gastric Metaplasia (1 paper, 2023). Intestinal metaplasia of the gastric mucosa is an intermediate precancerous gastric lesion in the gastric cancer cascade from chronic gastritis and atrophy to dysplasia and adenocarcinoma. "In a transgenic mouse gastric metaplasia model, we found that strains from unrelated individuals differed in their ability to infect the stomach, to colonize metaplastic glands, and to alter the expression of the metaplasia-associated protein TFF3." (PMID 36598261, 2023).
gastrointestinal adenoma (1 paper, 2015). "TFF3 expression is elevated during gastrointestinal adenoma progression and has been shown to promote mucosal wound healing." (PMID 26083576, 2015).
Giardia infection (1 paper, 2017). "This study also shows that Giardia infections increase the expression of another anti-microbial peptide, trefoil factor three (TFF3)." (PMID 28622393, 2017). "Further research is needed to assess the molecular pathway(s) by which Giardia infection could activate host defensive mechanisms that leads to the activation of AMPs and TFF3 production in the presence of an A/E enteropathogen." (PMID 28622393, 2017).